LRRTM2 (leucine rich repeat transmembrane neuronal 2)
Description:
Involved in the development and maintenance of excitatory synapses in the vertebrate nervous system. Regulates surface expression of AMPA receptors and instructs the development of functional glutamate release sites. Acts as a ligand for the presynaptic receptors NRXN1-A and NRXN1-B (By similarity).
Synonyms: KIAA0416
Tractability: Antibody: UniProt places it where antibodies can reach, with medium confidence; UniProt predicts a signal peptide or a membrane-spanning region; its Gene Ontology location is reachable by antibodies, with medium confidence. PROTAC: its protein half-life has been measured.
Gene: Protein-coding gene on chromosome 5 (138,868,921 to 138,875,368, reverse strand). Ensembl gene ENSG00000146006.
Subcellular location: Cell membrane; Postsynaptic cell membrane
Pathways (Reactome):
Neuronal System: Neurexins and neuroligins
Gene Ontology:
Molecular function: protein binding; neurexin family protein binding
Biological process: regulation of postsynaptic density assembly
Cellular component: GABA-ergic synapse; postsynaptic specialization membrane; excitatory synapse; glutamatergic synapse; hippocampal mossy fiber to CA3 synapse; plasma membrane; postsynaptic density membrane; postsynaptic membrane; Schaffer collateral - CA1 synapse; synapse
Genetic constraint (gnomAD): Loss-of-function variants: 14 observed, 39.7 expected, observed/expected ratio (o/e) 0.35, 90% interval 0.23 to 0.55. The upper end of that interval is the gene's LOEUF score, 0.55, which puts it in group 2 of 6, group 1 being the genes least tolerant of losing a copy. Missense variants: 464 observed, 646.94 expected, observed/expected ratio (o/e) 0.72, 90% interval 0.66 to 0.77. Synonymous variants: 222 observed, 248.99 expected, observed/expected ratio (o/e) 0.89, 90% interval 0.8 to 1.
Homologues: Orthologues: chimpanzee LRRTM2 (100% identical), macaque LRRTM2 (100% identical), dog LRRTM2 (99% identical), rabbit LRRTM2 (99% identical), guinea pig LRRTM2 (98% identical), mouse Lrrtm2 (98% identical), rat Lrrtm2 (98% identical), pig LRRTM2 (98% identical), zebrafish lrrtm2 (65% identical), Caenorhabditis elegans sma-10 (20% identical), Drosophila melanogaster kek3 (18% identical), Caenorhabditis elegans lron-9 (17% identical), and 1 more. Paralogues in human: LRIG1 (24% identical), LRIG3 (24% identical), TRIL (23% identical), LRIG2 (23% identical), LGR5 (22% identical), LGR4 (22% identical), CHADL (22% identical), LGR6 (20% identical), CPN2 (20% identical), LRRC24 (18% identical), LGI2 (15% identical), LRG1 (14% identical), and 10 more.
Diseases named in the same sentence as LRRTM2 in open-access papers:
LRRTM2 is named in the same sentence as 10 diseases in open-access papers, as found by Europe PMC text mining. Sharing a sentence is not in itself a finding about the gene and the disease. The quoted sentences say what the papers report.
heart failure (2 papers, 2024 to 2025). Inability of the heart to pump blood at an adequate rate to meet tissue metabolic requirements. "Key findings include the downregulation of proinflammatory genes, the identification of CXCL10 as a critical inflammatory biomarker mediating therapeutic effects, and the role of LRRTM2 in reducing heart failure risk." (PMID 40520225, 2025). "Another potential therapeutic approach is the modulation of LRRTM2 to improve cardiac resilience, particularly for patients with genetic predispositions to heart failure." (PMID 40520225, 2025). "In step 2 MR, pQTLs linked to LRRTM2 are utilized as the exposure, while heart failure (HF) is considered the outcome." (PMID 38725835, 2024). "On the other hand, the insufficiency of oxygen caused by heart failure can directly impact energy metabolism and gene expression in nerve cells, which may decrease the level of LRRTM2." (PMID 38725835, 2024). "According to leave-one-out analyses, the influence of LRRTM2 on heart failure (HF) did not seem to be significantly affected by any individual SNP." (PMID 38725835, 2024). "However, whether LRRTM2 mediates the impact of SGLT2 inhibition on heart failure in non-European populations warrants further exploration." (PMID 38725835, 2024).
schizophrenia (2 papers, 2017 to 2026). A major psychotic disorder characterized by abnormalities in the perception or expression of reality. "LRRTM2 is a maternally suppressed gene that is associated paternally with handedness and schizophrenia." (PMID 30090857, 2017). "Animal studies demonstrate that LRRTM2 plays an important role in hippocampal connectivity, and genetic studies show that NRXN1 is involved in a variety of neuropsychiatric traits, including schizophrenia, nicotine dependence and risk of suicide." (PMID 41044382, 2026).
Anxiety (1 paper, 2022). Intense feelings of nervousness, tension, or panic often arise in response to interpersonal stresses. "The region selective functions of LRRTM1 and LRRTM2 are further demonstrated by the lack of effect of Lrrtm1 and Lrrtm2 deletion in the dorsal hippocampus on social interaction or avoidance-related anxiety, which have been linked to the ventral hippocampus." (PMID 35662394, 2022). "Time spent in the inner and outer zones of the open field was equivalent between the genotyopes, indicating that deletion of Lrrtm1 and Lrrtm2 in the dorsal hippocampus does not increase risk-associated anxiety behavior." (PMID 35662394, 2022). "Thus, conditional deletion of Lrrtm1 and Lrrtm2 in dorsal hippocampus of adult mice does not alter avoidance-related anxiety behavior in mice." (PMID 35662394, 2022).
idiopathic dilated cardiomyopathy (1 paper, 2025). Decreased function of the heart associated with cardiac enlargement and congestive heart failure, of unknown cause. "Idiopathic dilated cardiomyopathy is linked to mutations in the NRXN1 gene, indicating that LRRTM2 may affect heart disease by controlling NRXN1." (PMID 40520225, 2025).
infection (1 paper, 2024). The state of being infected such as from the introduction of a foreign agent such as serum, vaccine, antigenic substance or organism. "LRRTM2 protein was strongly reduced upon Cre-recombinase infection, confirming the cKO of LRRTM2." (PMID 39394199, 2024).
neurological diseases (1 paper, 2024). "Lastly, given that LRRTM2 is a protein involved in synaptic formation, it suggests that SGLT2 inhibitors may have a certain regulatory effect on neurological diseases, thereby broadening the clinical application of SGLT2 inhibitors." (PMID 38725835, 2024).
LRRTM2 also shares sentences with these, for which no sentence is quoted: heart disease (2 papers); glioblastoma (1); nicotine dependence (1); tumor (1).